NAA15 (N-alpha-acetyltransferase 15, NatA auxiliary subunit)
Description:
Auxillary subunit of N-terminal acetyltransferase complexes which display alpha (N-terminal) acetyltransferase (NAT) activity. The NAT activity may be important for vascular, hematopoietic and neuronal growth and development. Required to control retinal neovascularization in adult ocular endothelial cells. In complex with XRCC6 and XRCC5 (Ku80), up-regulates transcription from the osteocalcin promoter.
Synonyms: GA19; NARG1; NATH; TBDN100; FLJ13340; MRD50; NAT1P; TBDN
Tractability: Small molecule: a structure with a bound ligand is known. PROTAC: ubiquitination databases record sites on it; its protein half-life has been measured.
Gene: Protein-coding gene on chromosome 4 (139,301,446 to 139,420,033, forward strand). Ensembl gene ENSG00000164134.
Subcellular location: Cytoplasm; Nucleus
Subcellular location (Human Protein Atlas): Cytosol; Cytokinetic bridge; Microtubules; Mitotic spindle; Nuclear bodies; Primary cilium; Vesicles
Gene Ontology:
Molecular function: acetyltransferase activity; protein binding; ribosome binding; RNA binding; acetyltransferase activator activity
Biological process: positive regulation of DNA-templated transcription; protein maturation
Cellular component: cytoplasm; cytosol; membrane; NatA complex; nuclear body; nucleus; transcription regulator complex
Genetic constraint (gnomAD): Loss-of-function variants: 12 observed, 44.44 expected, observed/expected ratio (o/e) 0.27, 90% interval 0.17 to 0.44. The upper end of that interval is the gene's LOEUF score, 0.44, which puts it in group 1 of 6, group 1 being the genes least tolerant of losing a copy. Missense variants: 281 observed, 440.19 expected, observed/expected ratio (o/e) 0.64, 90% interval 0.58 to 0.7. Synonymous variants: 152 observed, 153.31 expected, observed/expected ratio (o/e) 0.99, 90% interval 0.87 to 1.13.
Gene-disease validity (ClinGen):
ClinGen rates the evidence that NAA15 causes each of these diseases.
syndromic intellectual disability (autosomal dominant): Definitive. A intellectual disability that is part of a larger syndrome.
Homologues: Orthologues: dog NAA15 (99% identical), pig NAA15 (99% identical), mouse Naa15 (98% identical), chimpanzee NAA15 (98% identical), rat Naa15 (98% identical), macaque NAA15 (98% identical), rabbit NAA15 (97% identical), guinea pig NAA15 (97% identical), tropical clawed frog naa15 (89% identical), zebrafish naa15b (84% identical), zebrafish naa15a (80% identical), Drosophila melanogaster Naa15-16 (53% identical), and 1 more. Paralogues in human: NAA16 (70% identical), NAA25 (19% identical).
Diseases named in the same sentence as NAA15 in open-access papers:
NAA15 is named in the same sentence as 24 diseases in open-access papers, as found by Europe PMC text mining. Sharing a sentence is not in itself a finding about the gene and the disease. The quoted sentences say what the papers report.
Intellectual disability (8 papers, 2020 to 2024). "NAA15 (OMIM *608000) variants have been identified in patients with intellectual disability, speech delay, ASD, facial dysmorphology and cardiac anomalies (MIM # 617787)." (PMID 39415983, 2024). "PLoF variants and missense variants in NAA15 have been linked to a neurodevelopmental disorder with variable levels of intellectual disability, delayed speech and motor milestones, and autism spectrum disorder (MIM: 617787)." (PMID 40225914, 2024). "Truncating variants in NAA15 are associated with intellectual disability and congenital abnormalities." (PMID 34299277, 2021). "Since the initial clinical array was performed, haploinsufficiency of NAA15 has been associated with an autosomal dominant Mendelian neurodevelopmental syndrome (MIM 617787) characterized by variable levels of intellectual disability with global developmental delay and autism spectrum disorder." (PMID 35932041, 2022). "Regarding the recurring truncating NAA15 mutations, these have been associated previously with intellectual disability and congenital disorders, although not cancer." (PMID 32942614, 2020).
developmental delay (3 papers, 2022 to 2024). "The NDD phenotypes of this single exonic deletion, including delayed speech and language development and global developmental delay, were similar to those of NAA15 LGD variants, confirming the postulated mechanism of haploinsufficiency for NAA15." (PMID 35328089, 2022).
Ogden syndrome (2 papers, 2015 to 2024). Ogden syndrome is a rare, genetic progeroid syndrome characterized by a variable phenotype including postnatal growth delay, severe global developmental delay, hypotonia, non-specific dysmorphic facies with aged appearance and cryptorchidism, as well as cardiac arrthymias and skeletal anomalies. "The genetic landscape of variation in NAA10 and NAA15 in humans has been presented recently with many more cases of Ogden syndrome (OS) (also known as “NAA10-related neurodevelopmental syndrome”), and “NAA15-related neurodevelopmental syndrome”." (PMID 38713657, 2024).
attention deficit-hyperactivity disorder (1 paper, 2022). A disorder characterized by a marked pattern of inattention and/or hyperactivity-impulsivity that is inconsistent with developmental level and clearly interferes with functioning in at least two settings (e.g. at home and at school). "The NDD features of NAA15 variants are variable and include DD/ID, autism spectrum disorder (ASD), attention deficit hyperactivity disorder (ADHD), and motor and language disorders." (PMID 35328089, 2022).
autism (1 paper, 2021). Persistent deficits in social interaction and communication and interaction as well as a markedly restricted repertoire of activity and interest as well as repetitive patterns of behavior. "Protein-truncating mutations in NAA15 were reported in intellectual disability and autism patients, some of whom also presented a variety of cardiac abnormalities including ventricular septal defect, heterotaxy, pulmonary stenosis and tetralogy of Fallot." (PMID 34735430, 2021). "Additionally, 4 novel genes, POGZ, KDM5B, NAA15, and FRYL, harbored at least two de novo mutations in both CHD and autism cohorts." (PMID 34735430, 2021). "From this table, we can see CDK13, FRYL, LZTR1, NAA15 and PTEN have 2 DNM counts for CHD and at least 1 shared DNM count with autism." (PMID 34735430, 2021).
developmental disabilities (1 paper, 2025). "Recent genetic studies have identified mutations in the NAA15 gene in dozens of individuals, leading to NAA15-related syndrome, which shares clinical similarities with NAA10-related syndrome despite exhibiting variable degrees of developmental disabilities." (PMID 40558489, 2025).
glioblastoma (1 paper, 2020). The most malignant astrocytic tumor (WHO grade IV). "However, in another published study comparing normal with glioblastoma tissues, NAA30 and NAA80, which are associated with improved survival are downregulated, while NAA15, which is associated with worse survival, is upregulated." (PMID 32942614, 2020).
rickets (1 paper, 2024). Bone softening and weakening usually caused by deficiency or impaired metabolism of vitamin D. Deficiency of calcium, magnesium, or phosphorus may also cause rickets. "These molecular defects cause abnormal functions of the cartilage extracellular matrix (COMP), paracrine signalling factors (PHEX, FGFR3-related rickets), transcriptional regulation (LZTR1), histone methylation (KMT2A), posttranslational modification (NAA15), and mtDNA replication and repair (POLG)." (PMID 39415983, 2024).
cancer (5 papers, 2008 to 2025). A tumor composed of atypical neoplastic, often pleomorphic cells that invade other tissues. "Since NAA10 and its auxiliary subunit NAA15 are overexpressed in certain cancers, protein degraders targeting NAA10 or NAA15 offer a promising strategy to eliminate NAA10 in tumors where its overexpression drives tumorigenesis." (PMID 40558489, 2025). "In conclusion, our analyses of genomic alterations of NATs in cancers found these to be relatively low frequency events, with some notable exceptions, such as NAA40 amplification in UCS, and NAA15 truncating mutations in UCEC." (PMID 32942614, 2020). "Moreover, it has been reported that, although its function remains to be elucidated, the overexpression of NAA15 is strongly related with the cancer poor differentiation." (PMID 30944375, 2019). "To further narrow down the most relevant and likely direct targets of NAA10 in cancer, we merged these 123 and 46 proteins with the 173 N-terminally acetylated proteins identified in A431 cancer cells following siRNA knockdown of both NAA10 and NAA15." (PMID 40558489, 2025).
tumor (3 papers, 2020 to 2022). "Complementarily, the NAA15 gene was associated with cell proliferation in tumor cells, indicating a possible relationship between these genes and the mechanisms underlying cell proliferation and differentiation in the high groups due to the high cell activity in fat synthesis and storage." (PMID 35629975, 2022).
infection (2 papers, 2017 to 2025). The state of being infected such as from the introduction of a foreign agent such as serum, vaccine, antigenic substance or organism. "After infection, the yield loss of the NAA15‐OE plants was higher than that of the NAA15‐RNAi and NAA10‐RNAi plants." (PMID 40820884, 2025). "The response proteins DISP2 and NAA15 were among the most upregulated molecules, finding higher levels of expression at later stages of the infection." (PMID 28491823, 2017).
NAA15 also shares sentences with these, for which no sentence is quoted: autism spectrum disorder (2 papers); congenital heart disease (2); gastric cancer (2); microcephaly (2); Aicardi-Goutieres syndrome (1); breast carcinoma (1); congenital disorder of glycosylation type Im (1); intellectual disability syndrome (1); liver cancer (1); neurodevelopmental disorder (1); promyelocytic leukaemia (1); pulmonary hypertension (1); Ventriculomegaly (1).